CRP (C-reactive protein)
Diseases named in the same sentence as CRP in open-access papers (continued):
Sharing a sentence is not in itself a finding about the gene and the disease.
type 2 diabetes (continued). "Likewise, long-term filtered caffeinated and decaffeinated coffee consumption in healthy and type 2 diabetes women have been demonstrated to diminish inflammation, as indicated by lower levels of CRP, and prevent endothelial dysfunction, as assessed by a decrease in E-selectin." (PMID 39765784, 2024). "Even slight elevations in IL-6 and CRP levels, which may not manifest clinically, can heighten the risk of developing heart disease and type 2 diabetes in individuals who were previously considered healthy." (PMID 39685657, 2024). "However, previous studies on the association between hs-CRP and long-term outcomes in TVD patients with type 2 diabetes are scanty, and the prognostic value of hs-CRP in this patient population remains unknown." (PMID 37081535, 2023). "This supports the notion that reducing inflammatory processes, as measured by CRP, in addition to lowering insulin levels and improving insulin sensitivity, could contribute to protective effects against development of type 2 diabetes and progression of cardiometabolic disease." (PMID 36467859, 2022). "Although likely not a causal risk factor for disease itself, CRP lies downstream of multiple inflammatory pathways implicated in numerous chronic conditions, and has repeatedly been shown to predict risk of type 2 diabetes and cardiovascular disease (CVD) in later‐life." (PMID 35156387, 2022). "Our results indicate that CRP explained only a small proportion of the associations, suggesting that several other contributors might lie on the pathway between CVH metrics and diabetic complications and mortality among participants with type 2 diabetes." (PMID 36307875, 2022). "In fact, systemic inflammation measured by fibrinogen and C-reactive protein levels has been associated with nocturnal oxygen saturation parameters and the apnea–hypopnea index in snorers with compromised upper airway anatomy without type 2 diabetes." (PMID 35268504, 2022). "More broadly, a meta-analysis of trials investigating GLP-1RAs in people with type 2 diabetes demonstrated that GLP-1RA treatment was associated with significant reductions in CRP concentrations, with the duration of treatment associated with degree of CRP reduction." (PMID 36467859, 2022). "Interestingly, after exclusion of genetic instruments that were also associated with BMI, other metabolic factors (HDL, triglyceride, CRP, type 2 diabetes) had no causal effect on developing OA in the same study." (PMID 36233208, 2022). "Furthermore, in logistic regression analysis, the IIIA, IIIB, and IIIC groups with an alveolar bone resorption rate of 35% or more were associated with type 2 diabetes, regardless of the hs-CRP value." (PMID 35805792, 2022). "Moreover, a dysregulated immune system in patients with type 2 diabetes and chronic inflammation accompanied with elevated cytokine levels such as interleukin-6, tumor necrosis factor-α, and C-reactive protein could promote CRC tumorigenesis." (PMID 39131121, 2022). "Plasma C-reactive protein (CRP), an acute phase protein and marker of chronic low-grade inflammation, is associated with future cardiovascular risk in apparently healthy subjects and is an independent risk factor for coronary heart disease (CHD) deaths in type 2 diabetes." (PMID 34199645, 2021). "Consequently, GGT, hs-CRP, IFN-γ, ω-3 PUFAs, and dihomo-γ-linolenic acid emerged as independent predictors of WBC level alterations, and WBC levels appeared to be associated with the risk of type 2 diabetes, a chronic disease." (PMID 32346379, 2020). "Hayashino and colleagues demonstrated that elevated hs-CRP levels could increase the risk of development, not progression of albuminuria in patients with type 2 diabetes after 1 year of follow-up." (PMID 32587865, 2020).
type 2 diabetes (continued). "Whilst markers of inflammation were not measured in this study, it has been noted that inflammatory markers such as CRP are reduced by soy with isoflavones in type 2 diabetes, and therefore an effect on inflammation may have an indirect and positive effect on glycemic control." (PMID 31143160, 2019). "Therefore, we believe that the relationship between elevated serum hs-CRP level and increased prevalence of type 2 diabetes may be explained in part by increased BMI; however, other mechanisms likely contribute to this relationship." (PMID 28361994, 2017). "Elevated CRP levels (OR 1.44, 95% CI 0.99, 2.08) and elevated blood pressure (OR 1.36, 95% CI 0.92, 2.01) demonstrated positive but non-statistically significant associations with type 2 diabetes." (PMID 27227974, 2016). "Thus, CARDS does not yield any evidence to support the use of CRP as an indicator of efficacy of statin therapy on CVD risk in patients with type 2 diabetes." (PMID 25899452, 2015). "Hence the “high” CRP subgroup may represent a subgroup among patients with type 1 diabetes which may share some features with type 2 diabetes." (PMID 22448235, 2012). "Additionally the trend shown with CRP supports our hypothesis that inflammation of either infectious or non-infectious etiologies is associated with ICU delirium and coma." (PMID 21366899, 2011). "A positive association of HOMA-IR with CRP concentration was still evident after adjusting for waist circumference, indicating that this relationship was independent of abdominal obesity in the patients with type 2 diabetes." (PMID 21167068, 2010). "In clinical studies, curcumin supplementation reduced C-reactive protein (CRP) and other inflammatory markers, confirming its pronounced anti-inflammatory effects in patients with type 2 diabetes." (PMID 41599361, 2026). "Biomarkers such as TNF-α, CRP, and IL-6 showed strong correlations with nausea, diarrhea, abdominal pain, and bloating, with the most severe symptoms observed in the ART + type II diabetes group." (PMID 39860995, 2025). "The connection between well-known inflammatory markers such as C-reactive protein (CRP), IL-6, IL-8, TNF-α, and endothelin-1 and DAN has been established in patients with type 1 and type 2 diabetes." (PMID 40137134, 2025). "Adipose tissue produces TNF-α, and when its concentrations together with C-reactive protein (CRP) increase in the serum, it can contribute to the development of type-2 diabetes." (PMID 39932461, 2025). "Firstly, it provides new insights into the correlation between elevated inflammatory biomarkers—such as CRP, IL-6, TNF-α, and fibrinogen—and gastrointestinal symptoms in HIV-positive patients on ART, particularly those with type II diabetes." (PMID 39860995, 2025). "Moreover, the elevated plasma levels of C-reactive protein (CRP) and other pro-inflammatory cytokines such as interleukin-6 (L-6) and Tumor necrosis Factor-alpha (TNFα) were reported to induce pancreatic beta cell atrophy and dysfunction in type 2 diabetic rats." (PMID 39859066, 2025). "In individuals with type 2 diabetes, increased consumption of UPF predicted cardiovascular outcomes, with a detectable mediation by CRP and BMI, among other variables." (PMID 41010537, 2025). "Elevated levels of inflammatory markers such C-reactive protein (CRP), interleukin-6 (IL-6), and tumor necrosis factor-α (TNF-α) are commonly observed in patients with type 2 diabetes." (PMID 39224122, 2024). "There were other cross-trait correlation pairs such as type 2 diabetes and HDL cholesterol, CRP and BMI." (PMID 38459230, 2024). "However, bidirectional one- and two-sample genetic Mendelian randomization analyses did not support causality between CRP and glucose, indicating that inflammation and type 2 diabetes are correlated but independent risk factors of cardiovascular disease and death." (PMID 38730445, 2024).
type 2 diabetes (continued). "Biomarkers of inflammation such as circulating C-reactive protein (CRP), an indicator of innate immune activity, are known to be elevated in men and women with type 2 diabetes." (PMID 38725572, 2024). "Further research identified a correlation between H. pylori infection and elevated levels of inflammatory markers, such as C-reactive protein (CRP), in patients with type 2 diabetes." (PMID 39202269, 2024). "The effect of atorvastatin on CRP levels and its implications for CVD in patients with type 2 diabetes was assessed by Soedamah-Muthu and colleagues." (PMID 37760885, 2023). "Among novel biomarkers studied 25(OH)D, CRP, and LBP significantly predicted incidence of any cardiovascular event or total mortality in a group of patients with type 2 diabetes during a mean 5.6-year follow-up when analyzed separately." (PMID 37623831, 2023). "Age, alcohol consumption, BMI, CRP, HDL-cholesterol, history of type 2 diabetes, SBP, serum zinc, smoking status, socioeconomic status, total cholesterol." (PMID 37441705, 2023). "In another study, besides CRP, TNF was also found to be an independent predictor of diabetic kidney disease in type 2 diabetes patients." (PMID 37762893, 2023). "This novel inflammatory biomarker has a positive predictive value for the future development of type 2 diabetes and CVD independently of CRP in different cohorts, especially in young individuals." (PMID 36361733, 2022). "Similar results have also been observed in people with type 2 diabetes; in the randomised, open-label, multinational 52-week PIONEER 2 trial, oral semaglutide 14 mg resulted in a significantly greater reduction in CRP compared with empagliflozin 25 mg." (PMID 36467859, 2022). "This study investigated the association of selected salivary inflammatory biomarkers (Interleukin 6 [IL-6], C-reactive protein [CRP], and Tumour necrosis factor α [TNF-α]) to glycated haemoglobin (HbA1C) in type 2 diabetics." (PMID 33676486, 2021). "Elevated serum concentrations of inflammatory biomarkers, e.g., C-reactive protein (CRP), interleukin (IL) 6, or IL 18 were found in humans with type 2 diabetes." (PMID 34639176, 2021). "OASL was downregulated and has shown effects on C-reactive protein, γ glutamyltransferase and LDL-cholesterol, which are all related to cardiovascular events that are frequent in individuals with type 2 diabetes as well as inflammation." (PMID 33973017, 2021). "The MR estimates for CRP, HDL-C and triacylglycerol levels exceeded and were statistically heterogeneous to those obtained for reduced type 2 diabetes liability more generally, suggesting additional mechanisms specific to GIP signalling." (PMID 34505161, 2021). "Anti- inflammatory activity such as inhibition of c reactive protein (CRP), TNF-α, IL-6, IL8 and IL-10 was observed in type 2 diabetics." (PMID 33261642, 2020). "A recent study has also reported a link between hs-CRP elevation and urinary alpha-1 microglobulin (A1MG), an early sign of renal damage, in type II diabetes patients." (PMID 32823680, 2020). "Compared with the control subjects, the values of BMI, HbA1C, TC, TG, LDL-C, CRP, Fins, HOMA-IR and skin AF were significantly increased (P<0.05), whereas the levels of irisin and HDL-C were significantly lowered (P<0.05) in type 2 diabetic patients." (PMID 28408433, 2017). "Median serum levels of CRP, triacylglycerol, plasma glucose and HOMA-IR were higher among those who developed type 2 diabetes, whereas ApoA-1 levels were lower." (PMID 28612106, 2017). "A-FABP was significantly correlated with glycated hemoglobin A1C (HbA1C), BMI, triglyceride, Homeostasis Model Assessment Index (HOMA-IR), waist hip rate, C-reactive protein, IL-6, and HDL-C in obese subjects with type 2 diabetes." (PMID 27819006, 2016).
type 2 diabetes (continued). "The results of the current study showed that HbA1C, BMI, TG, HOMA-IR, WHR, CRP, and IL-6 were positively correlated with serum A-FABP, and HDL-C was negatively correlated with A-FABP in obese subjects with newly diagnosed type 2 diabetes." (PMID 27819006, 2016). "The Women’s Health Study, a prospective study about the health of middle-aged women in the USA found that elevated level of C-reactive protein (CRP) and interleukin-6 (IL-6) predict development of type 2 diabetes in women." (PMID 27581604, 2016). "This review reported a statistically significant improvement in CRP and TNF-α serum levels after periodontal therapy in people with a number of comorbidities but not limited to type 2 diabetes." (PMID 26010492, 2015). "The main finding of the review was that hs-CRP and TNF-α were statistically significantly lowered by PT in people with type 2 diabetes when compared to controls." (PMID 26010492, 2015). "In multivariate analyses, male gender, type 2 diabetes, a history of CVD, hemoglobin, albumin and GFR lost significance, while older age, the extent of proteinuria and higher CRP-levels remained significantly related to mortality (all p<0.05)." (PMID 25894587, 2015). "HA or use of HA drugs, previous CVD, higher level of RAGE and CRP, older age and less years of formal education are the factors increasing the likelihood of having MCI in elderly patients with type 2 diabetes in multivariable model." (PMID 26578953, 2015). "HA or use of HA drugs, previous CVD, higher level of RAGE and CRP, older age and less years of formal education are the factors increasing the likelihood of having MCI in elderly patients with type 2 diabetes." (PMID 26578953, 2015). "Few reports are available on the correlation between hs-C-reactive protein (hs-CRP) and cardiovascular disease in type 2 diabetes patnts." (PMID 26153197, 2015). "We also found that the monocyte count in patients with type 2 diabetes was positively correlated with SBP, TG, CCA-IMT and hs-CRP, but negatively correlated with HDL cholesterol." (PMID 24373412, 2013). "Others report that aerobic exercise training decreases plasma CRP, TNF-α and IL-18/IL-10 ratios in type 2 diabetics." (PMID 24324580, 2013). "In recent years systemic inflammation - which can be measured by high sensitivity C-reactive protein (hs-CRP) - has become an important marker for cardiovascular disease and type 2 diabetes." (PMID 22417460, 2012). "However, we could not address the association between inflammation and type 2 diabetes because most study subjects did not have available measurements of inflammatory markers such as CRP and IL-6." (PMID 22524685, 2012). "Therefore, patients with type 2 diabetes who are, usually obese, could potentially have high CRP." (PMID 23675214, 2011). "Similar statistical analysis in Group D (patients with type 2 diabetes & LVDD) revealed that sST2 levels positively correlated with HbA1c (p < 0,01) and hs-CRP levels (p = 0,042) and negatively only with HDL (p = 0.041)." (PMID 22104207, 2011). "Both low birth weight, an indicator of intrauterine growth restriction, and low grade systemic inflammation depicted by high sensitivity C-reactive protein (hs-CRP) have emerged as independent predictors of cardiovascular (CV) disease and type 2 diabetes." (PMID 21418637, 2011). "In a prospective study of 125 people with Type 2 diabetes, ADMA, L-arginine and C-reactive protein (CRP) levels were measured." (PMID 21532773, 2010). "The optimal value of cut-off point for hs-CRP and probability value of regression model to predict CAD in patients with type 2 diabetes were 5.2 mg/l and 0.648, respectively." (PMID 17178005, 2006). "In the present study, levels of inflammatory markers were higher in the morning among type 2 diabetic cohorts, whereas NT-proBNP and CRP were elevated in the afternoon for participants without type 2 diabetes." (PMID 40580209, 2025).
type 2 diabetes (continued). "Previous clinical trials have shown that liraglutide reduced albuminuria, which is thought to be a biomarker of microvascular and macrovascular endothelial dysfunction, as well as circulating levels of various inflammatory markers, including CRP, TNF‐α and IL‐6 in individuals with type 2 diabetes." (PMID 40276845, 2025). "Participants with type 2 diabetes had higher CRP and NT-proBNP levels in the morning, whereas non-diabetic participants showed higher levels in the afternoon." (PMID 40580209, 2025). "In this cross-sectional analysis, 8.5% of the individuals had type 2 diabetes, and the median CRP concentration was not elevated." (PMID 38999806, 2024). "Cumulative incidences of IHD and CVD death were 365% and 592% higher, respectively, in individuals with both type 2 diabetes and plasma CRP ≥ 2 mg/L compared to individuals without either." (PMID 38730445, 2024). "When comparing the results of the present study with those of the previous SUKALMENA study, some differences in biochemical parameters (CRP and cholesterol measurements, especially HDL-c) were noted, probably due to the fact that the SUKALMENA study was conducted with patients with type 2 diabetes." (PMID 38892668, 2024). "Men with NAFLD were more obese and more centrally obese, had higher concentrations of ALT, LDLC, TAG, glucose, insulin, hs-CRP, and FFAs, and more often had type 2 diabetes than men without NAFLD." (PMID 36837886, 2023). "In addition, these chronic inflammatory markers (IL-6, CRP, and TNF-alpha, among others) are associated with several different diseases, including infection, cardiovascular disease, and type 2 diabetes mellitus (T2DM)." (PMID 35053667, 2022). "A basic model including sex, age, type 2 diabetes mellitus (T2DM), smoking, body mass index, total cholesterol, C-reactive protein, blood pressure, eGFR, and angiographically determined significant coronary artery disease (CAD) was built as a linear predictor score after Cox regression." (PMID 35496482, 2022). "Future studies are needed to compare the levels of these proteins between patients with type I vs. type II diabetes to differentiate whether type I and type II diabetes have different effects on the expression of ASC, IL-18, CRP, uPA, EGF, and NGAL." (PMID 35355862, 2022). "Studies have indicated that myosteatosis is associated with insulin resistance, type 2 diabetes mellitus (T2DM), dyslipidemia and cardiometabolic diseases, and there was also a link between skeletal muscle density and biomarkers of inflammation, such as CRP, IL-6, TNF-α, adiponectin and leptin." (PMID 35837298, 2022). "Our previous study showed increased valvular expression of C-reactive protein (CRP) and its mRNA, and higher tissue factor (TF) expression in individuals with AS and concomitant type 2 diabetes compared with non-diabetic individuals." (PMID 34494136, 2021). "Additionally, plasma levels of C-reactive protein (CRP), tumor necrosis factor-α (TNF-α), and interleukin-6 (IL-6) are elevated in subjects with type 2 diabetes, indicating the existence of low-grade systemic and hyperglycemia-induced inflammation." (PMID 33536442, 2021). "There was evidence of a larger association of genetically proxied GIP signalling compared with genetically proxied reduced type 2 diabetes liability more generally for CRP, HDL-C and triacylglycerol levels (all p < 0.001), but not strongly for BMI (p = 0.07)." (PMID 34505161, 2021). "In patients with type 2 diabetes a relation between higher plasma levels of high-sensitivity C-reactive protein (hs-CRP) and non-fatal and fatal cardiovascular events have been shown." (PMID 34753497, 2021). "However, compared with patients in the lowest FGF-23 tertile, those with higher FGF-23 levels were older, had a greater prevalence of type 2 diabetes and CKD, and were more likely to present with higher levels of serum phosphate and CRP at baseline." (PMID 34297744, 2021).